FOS (Fos proto-oncogene, AP-1 transcription factor subunit)
Diseases named in the same sentence as FOS in open-access papers (continued):
Sharing a sentence is not in itself a finding about the gene and the disease.
Sepsis (4 papers, 2022 to 2026). Sepsis is defined as life-threatening organ dysfunction caused by a dysregulated host response to infection. "In Astrocyte 1, inflammation-associated genes (GFAP, FOS, C3, CD74) were significantly upregulated, while BBB-related genes (GRIA2, NRGN, TXNIP) were downregulated in sepsis." (PMID 41030458, 2025). "Moreover, the downstream TFs targeted by the LR pairs in sepsis-induced ARDS are FOS, RB1, STAT2, and STAT3." (PMID 35222683, 2022). "Furthermore, we analyzed the downstream TFs targeted by LR pairs and found that different TFs, including SMAD3, RBPJ, and MAX, were targeted in sepsis-only patients, while FOS, STAT3, STAT2, and RB1 were targeted in sepsis-induced patients." (PMID 35222683, 2022).
squamous cell lung carcinoma (4 papers, 1998 to 2023). A carcinoma arising from squamous bronchial epithelial cells. "For this reason, immunohistochemistry was used to examine the squamous cell lung carcinomas from 121 patients for their expression of ERBB-1, vascular endothelial growth factor (VEGF), cyclin A, FOS, JUN and MYC." (PMID 9484827, 1998).
triple-negative breast carcinoma (4 papers, 2016 to 2026). An invasive breast carcinoma which is negative for expression of estrogen receptor (ER), progesterone receptor (PR), and human epidermal growth factor receptor 2 (HER2). "Fos proto-oncogene, AP-1 transcription factor subunit (FOS) suppresses tumor growth in triple-negative breast cancer while enhancing inflammatory responses that recruit neutrophils." (PMID 41123022, 2026).
type 2 diabetes (4 papers, 2017 to 2021). "These signaling pathways contained the significant gene regulatory network of transcript factors families for type 2 diabetes including SP1, NFIC, ZFP161, and FOS, JUND, JUNB." (PMID 28179884, 2017). "FOS, IGF1R, IGF2, FOXO1, and NTF3 might target “TGF-β signaling pathway”, “the hedgehog signaling pathway”, “retinol metabolism”, or “type II diabetes mellitus” pathways respectively." (PMID 32694937, 2020). "Based on the ceRNA network, we also discovered that FOS, IGF1R, IGF2, FOXO1, and NTF3 might target the “TGF-β signaling pathway”, “the hedgehog signaling pathway”, “retinol metabolism”, or “type II diabetes mellitus” pathways respectively, thereby modulating the subsequent development of ICC." (PMID 32694937, 2020).
vascular tumors (4 papers, 2020 to 2025). "Rearrangements in FOSL1 and FOS were identified in 10/15 and 2/15 desmoplastic fibroblastomas respectively, which mirrors the pattern of FOS rearrangements observed in benign bone and vascular tumours." (PMID 36426824, 2023). "Additionally, gene fusions involving FOS, FOSB, YAP1, and WWTR1 have been discovered in vascular tumors, improving diagnostic accuracy." (PMID 40428263, 2025). "ALHA is currently considered a vascular neoplasm with known FOS and FOSB gene rearrangements." (PMID 36611215, 2023). "Similar rearrangements of FOS and FOSB were previously found in vascular tumors." (PMID 31768625, 2020).
acute kidney injury (3 papers, 2011 to 2025). Sudden and sustained deterioration of the kidney function characterized by decreased glomerular filtration rate, increased serum creatinine or oliguria. "Recent research has revealed that FOS can affect the transcription of inflammatory cytokines by binding to their promoters, leading to their high expression inducing endotoxin-induced and cisplatin-induced acute kidney injury (AKI)." (PMID 34703677, 2021).
allergic rhinitis (3 papers, 2021 to 2024). Inflammation of the nasal mucous membranes caused by an IgE-mediated response to external allergens. "This study verified that the role of FOS in allergic rhinitis nasal epithelial cell proliferation (apoptosis) effects at a cellular level, and verified the results in the gene expression profile of nasal mucosal tissue in previous experiments." (PMID 34383804, 2021). "1Compared with healthy controls, miR-29a expression was up-regulated and FOS mRNA expression was down-regulated in the nasal tissues from the patients with allergic rhinitis (AR)." (PMID 34383804, 2021).
Atrophy (3 papers, 2025 to 2026). Any weakening or degeneration, especially through lack of use. "KLF5 and KLF10 are key mediators of early muscle atrophy, whereas FOS increases after denervation‐induced muscle atrophy." (PMID 39435630, 2025).
autoimmune disease (3 papers, 2022 to 2024). A disorder resulting from loss of function or tissue destruction of an organ or multiple organs, arising from humoral or cellular immune responses of the individual to their own tissue constituents. "For example, Asian-specific haQTLs provided novel candidate variants in gene loci associated with leprosy (SIGLEC5, TNFSF15) and autoimmune disease (CARD9, IRF5, IL27, FOS) (nd 48)." (PMID 35102304, 2022). "Genes related to these autoimmune diseases and Th17 cell differentiation, including CTLA4, IFN-ALPHA-8, IL12RB2, TRAV3, TRAV16, FOS, and VEGFA, were up-regulated in the E. coli group but down-regulated in the BL + E." (PMID 39707535, 2024).
bipolar disorder (3 papers, 2009 to 2014). A disorder of the brain that causes unusual shifts in mood, energy, activity levels and the ability to carry out day-to-day tasks. "For example, one researcher of bipolar disorder found interactions involving FOS, which he knew to be associated with response and non-response to lithium treatment." (PMID 19216777, 2009).
brain injury (3 papers, 2013 to 2022). Acute and chronic (see also brain INJURIES, CHRONIC) injuries to the brain, including the cerebral hemispheres, CEREBELLUM, and brain STEM. "The FOS and EGR1 genes belonging to the immediate-early gene (IEG) family have been reported to be induced by a secondary insult following brain injuries." (PMID 36564820, 2022).
cardiomyopathy (3 papers, 2023 to 2025). A disease of the heart muscle or myocardium proper. "Therefore, we hypothesized that FOS may influence with the development of cardiomyopathy through protein hydrolysis and cell cycle progression." (PMID 38799173, 2024). "Additionally, stemness genes EPAS1 and MYC, along with the regulator FOS, may play roles in modulating the biological processes of cardiac fibroblasts in cardiomyopathy." (PMID 38799173, 2024). "Microvascular network growth and the angiogenic properties of the TAT in elderly patients with cardiomyopathy also seem to involve the upregulation of PDGFC, FGF2, NOTCH2, FOS, JAG1, and PDGFRA target genes." (PMID 37833902, 2023). "The transcription factors FOS, FOSB, and JUNB may help prevent adverse events such as cardiac fibrosis in cardiomyopathy." (PMID 40717095, 2025). "Based on the findings of cell type-specific regulatory activity, the most active TFs in each of the 4 cardiomyopathy fibroblast subpopulations, including NR3C1 (C0 THBS4+ Fibroblasts), KLF4 (C1 LINC01133+ Fibroblasts), FOSB (C2 FGF7+ Fibroblasts), FOS (C3 AGT + Fibroblasts)." (PMID 38799173, 2024).
cerebral infarction (3 papers, 2017 to 2025). An ischemic condition of the brain, producing a persistent focal neurological deficit in the area of distribution of the cerebral arteries. "Through bioinformatics analysis, we identified key targets associated with cellular senescence and circadian rhythm in cerebral infarction, specifically CREBBP, FOS, CDK4, MMP9, PTEN, and HIF1A." (PMID 40629591, 2025).
diabetic nephropathy (3 papers, 2022 to 2025). "We first identified the expression level of CCL2, FOS, JUN in IgAN, lupus nephritis, diabetic nephropathy, focal segmental glomerulosclerosis, minimal change disease, and membranous glomerulonephropathy, respectively." (PMID 35464092, 2022).
esophageal cancer (3 papers, 2009 to 2022). A primary or metastatic malignant neoplasm involving the esophagus. "In this study, FOS was discovered as a diagnostic biomarker with poor prognosis in esophageal cancer." (PMID 36569220, 2022). "Next, we analyzed the expression of these four important genes (VCAN, ANGPT2, MS4A4A, and FOS) between esophageal cancer and normal esophageal tissues." (PMID 36569220, 2022). "Among 182 genes, four genes including ANGPT2, VCAN, MS4A4A, and FOS had significant prognostic value in esophageal cancer." (PMID 36569220, 2022). "Four genes including ANGPT2, VCAN, MS4A4A, and FOS were considered to have significant prognostic value in esophageal cancer." (PMID 36569220, 2022). "In the total 182 hub genes, four hub genes including ANGPT2, VCAN, MS4A4A, and FOS had significant prognostic value in esophageal cancer." (PMID 36569220, 2022). "In our study, microarray data showed that three genes (FOS, JUN, BIRC5) associated with the anti-apoptotic response were elevated in the cisplatin-treated esophageal cancer cells." (PMID 24959694, 2014). "Thus, we considered that hub genes including ANGPT2, VCAN, MS4A4A, and FOS were involved in the pathogenesis of esophageal cancer." (PMID 36569220, 2022). "We found that compared with normal human esophageal tissues, ANGPT2, VCAN, and FOS were significantly upregulated in esophageal cancer tissues, MS4A4A was significantly downregulated in esophageal cancer." (PMID 36569220, 2022). "High levels of ANGPT2, FOS, and MS4A4A were correlated with poor prognosis of esophageal cancer, while high level of VCAN was correlated with better prognosis of esophageal cancer." (PMID 36569220, 2022). "High levels of ANGPT2, FOS, and MS4A4A were correlated with poor prognosis of esophageal cancer, while high levels of VCAN were correlated with better prognosis of esophageal cancer." (PMID 36569220, 2022). "Thus, FOS and MS4A4A might participate in the function of macrophages in esophageal cancer." (PMID 36569220, 2022).
Glomerular sclerosis (3 papers, 2019 to 2022). Accumulation of scar tissue within the glomerulus. "One recent study demonstrated that FOS expression was enriched in IgAN patients with important roles in mesangial proliferation and glomerular sclerosis." (PMID 33936064, 2021). "FOSL1 and FOSL2 are also members of the FOS gene family and overexpressed in various renal diseases like IgAN, lupus nephropathy, and focal glomerular sclerosis, with pivotal roles in glomerular sclerosis and mesangial proliferation." (PMID 31392215, 2019). "FOS was significantly overexpressed in proximal tubule cells of HBV-MN, which plays a crucial role in mesangial proliferation and glomerular sclerosis." (PMID 35935760, 2022).
gouty arthritis (3 papers, 2013 to 2020). "The therapeutic targets through which Simiao decoction alleviated gouty arthritis were p-STAT3, APOB, CASP8, c-FOS, PPARα, FN1, and LPL." (PMID 32670069, 2020).
head and neck squamous cell carcinoma (3 papers, 2018 to 2024). A squamous cell carcinoma that arises from any of the following anatomic sites: lip and oral cavity, nasal cavity, paranasal sinuses, pharynx, larynx, and salivary glands. "The increased expression of the FOS gene can trigger the VEGF (vascular endothelial growth factor) and enhance NANOG and c-myc genes in head and neck squamous cell carcinoma." (PMID 35216085, 2022).
Infertility (3 papers, 2016 to 2025). "Interestingly, our study observed elevated expression of FOS and FOSB in the SA group, while a previous study reported a decrease in expression of these genes among infertile men." (PMID 40938846, 2025).
insomnia (3 papers, 2022 to 2025). A sleep disorder characterized by difficulty in falling asleep and/or remaining asleep.
intervertebral disc degeneration (3 papers, 2018 to 2025). "Elevated expression of FOS aggravates oxidative damage and promotes cell death, thereby contributing to the progression of intervertebral disc degeneration." (PMID 40901474, 2025).
keloid (3 papers, 2021 to 2024). An irregularly shaped, elevated mark on the skin caused by deposits of excessive amounts of collagen during wound healing. "We identified four subpopulations of endothelial cells in keloid and normal scar tissue by scRNA-seq data: MMP1+ Endo0, FOS + JUN + Endo1, IL6+CSF3+ Endo2, CXCL12 Endo3." (PMID 36082167, 2022).
lymph node metastasis (3 papers, 2022 to 2024). "In addition, FOS and FOSB were downregulated when lymph node metastasis was present, while CD27 and SELL were upregulated." (PMID 35037412, 2022).
mesenchymal tumor (3 papers, 2015 to 2024). "The FOS gene family has been implicated in tumourigenesis across several tumour types, particularly mesenchymal tumours." (PMID 36426824, 2023). "Forty-five different mesenchymal tumor forms, including pleomorphic sarcoma with epithelioid characteristics and epithelioid sarcoma, which may mimic PF/PM, showed negative results for c-FOS immunohistochemistry." (PMID 39070491, 2024).
metastatic tumors (3 papers, 2015 to 2025). "In comparison with the control group, there was a significant decrease in the positivity rates of Ly6G, MPO, CitH3, and c-FOS in the metastatic tumors of the treatment group." (PMID 40148973, 2025).
mood disorder (3 papers, 2018 to 2025). A cognitive disorder a disturbance in which the person's mood is hypothesized to be the main underlying feature. "Many genes, e.g. FOS, DUSP1 and HNRNPA1, were up-regulated in more than one condition, suggesting potential molecular links between sleep deprivation and mood disorders." (PMID 34691834, 2019).
muscle atrophy (3 papers, 2020 to 2026). The loss of muscle tissue due to inactivity or disease. "In summary, we identified miR‐29b‐3p as a muscle atrophy‐associated exosomal miRNA with potential to be uptake by neuronal cells which consequently inhibits neuronal cell differentiation via targeting the mRNAs of c‐FOS, BCL‐2, RIT1, LAMC1, and upregulation of lncRNA HIF1α‐AS2." (PMID 32233025, 2020). "TEAD4, FOS and MYC are essential for embryonic skeletal muscle development, activation of these regulons in RCT implicates the activation of an early developmental program in the pathogenesis of muscle atrophy." (PMID 39435630, 2025).
myeloid leukemia (3 papers, 2014 to 2025). A clonal proliferation of myeloid cells and their precursors in the bone marrow, peripheral blood, and spleen. "As this step marks the transition to an acute leukemia, the overlapping genes (CEBPB, FOS, FOSB, IL8, S100A12, SOCS2) might be involved in the aggressiveness of MLL-AF9 myeloid leukemia blasts." (PMID 24517546, 2014).
papillary thyroid carcinoma (3 papers, 2012 to 2025). "As far as the papillary thyroid carcinomas are concerned, FOS, FOSB and EGR1 genes were down-regulated, like CBX7, while SPP1, SPINK1 and STEAP1 were up-regulated." (PMID 24865347, 2014). "Specifically, noteworthy are our findings regarding the potential diagnostic value of CCNA1 and SFN genes in papillary thyroid carcinoma, while the reduced expression of CDKN1C, FOS, and JUN genes in follicular carcinoma suggests their value in distinguishing the thyroid pathologies." (PMID 40722651, 2025).
pterygium (3 papers, 2009 to 2024). A wedge-shaped fibrovascular lesion arising from the bulbar conjunctiva and extending to the cornea. "As the NESs of the antioxidant and cytokines/chemokines indicated their positive enrichment in pterygiums in both Asian and European samples, GSTA1, PARL, and FOS might contribute to their upregulation in response to oxidative stress and DNA damage." (PMID 38732006, 2024).
renal carcinoma (3 papers, 2010 to 2024). A carcinoma arising from the epithelium of the renal parenchyma or the renal pelvis. "Previous studies have highlighted the downregulation of CEBPD in RCC and the association of FOS and JUNB with renal cancer." (PMID 38292868, 2024).
steatosis (3 papers, 2011 to 2025). Increased lipid within the cytoplasm of cells. "Of the top-ranked 10 genes, two genes (CYP7A1 and PEG10) were significantly up-regulated in both steatosis and NASH patients, while eight genes (FOSB, FOS, IL6, GADD45G, MYC, SLITRK3, JUNB, and IGFBP2) were significantly down-regulated." (PMID 33324350, 2020). "In addition, FOS treatment decreased fasting glycemia and lowered the higher expression of key factors involved in the fatty acid catabolism observed in the liver of n-3/-mice, without lessening steatosis." (PMID 21707971, 2011).
systemic lupus erythematosus (3 papers, 2013 to 2022). An autoimmune multi-organ disease typically associated with vasculopathy and autoantibody production. "Besides FOS, FOXO1, and FOXO3, upregulated TBK1 and TNFSF10 contributed to the activation prediction of ‘Systemic Lupus Erythematosus In B Cell Signaling’." (PMID 35406685, 2022).
vitiligo (3 papers, 2022 to 2025). Generalized well circumscribed patches of leukoderma that are generally distributed over symmetric body locations and is due to autoimmune destruction of melanocytes. "Compared with the healthy controls, monocyte subpopulations expressed high levels of HLA-DRA, FOS, and the uncharacterized gene AC253572.2 in vitiligo patients." (PMID 41438750, 2025). "We verified that FOS and HLA-DRB5 expression was upregulated in PBMC from vitiligo patients compared with HCs by analyzing Bluk-RNA seq data from GEO database." (PMID 38077333, 2023). "After experimental verification for several markedly altered candidates, FOS and RGS19 were confirmed to be significantly high in vitiligo lesions, which was in line with the results from our RNA-seq dataset." (PMID 35406685, 2022). "qRT-PCR confirmed the significant increases in FOS and RGS19 in vitiligo lesions." (PMID 35406685, 2022). "FOS and RGS19 were confirmed to have significant increases in vitiligo patients." (PMID 35406685, 2022).
allergic reaction (2 papers, 2019 to 2021). "we will continue to explore the relationship among immune reaction, allergic reaction and MiR-29a/FOS in the later study." (PMID 34383804, 2021). "Therefore, additional studies should clarify the role of FOS during allergy protection." (PMID 30800003, 2019).
Arrhythmia (2 papers, 2022). Any cardiac rhythm other than the normal sinus rhythm. "However, the involvement of other genes, including CXCL8, FOS, CCL2, and MMP9, in aconitine-induced arrhythmias warrants further research." (PMID 35915792, 2022).
autoimmune conditions (2 papers, 2010 to 2022). "This could help in studying the subsequent changes in the Th17-regulatory roles of FOS and ATF proteins, which potentially associates with the development of autoimmunity." (PMID 35511484, 2022).
brucellosis (2 papers, 2018 to 2024). Brucellosis is a bacterial infection that spreads from animals to people via unpasteurized dairy products or by exposure to contaminated animal products or infected animals. "Interestingly, a series of commonly upregulated genes were identified in brucellosis patients, with seven genes/transcription factors (RGS1, DUSP1, FOS, PPP1R15A, TNFAIP3, HLA‐E, and ZFP36) being the most frequent (nine times among nine clusters)." (PMID 39135683, 2024).
Cirrhosis (2 papers, 2022 to 2024). A chronic disorder of the liver in which liver tissue becomes scarred and is partially replaced by regenerative nodules and fibrotic tissue resulting in loss of liver function. "Several oncogenic transcription factors (TFs) inferred with DoRothEA35 including FOS, ETS2, RELB, SOX10, ERG, WT1 and JUND and TFs supporting stemness such as PBPJ and ARID3A were upregulated in cirrhosis patients and correlated with bacterial translocation." (PMID 35803930, 2022).
cystic fibrosis (2 papers, 2006 to 2022). Autosomal recessive disorder caused by pathogenic variants in the CFTR gene (cystic fibrosis transmembrane conductance regulator), which encodes a chloride and bicarbonate channel expressed in epithelial cells, and follow the diagnosis criteria. "While the FOS gene is known to be associated with apoptosis, CXCL8-mediated recruitment and activation of neutrophils is responsible for causing pathogenesis of lower respiratory tract infection and if overproduced, leads to cystic fibrosis." (PMID 36532041, 2022).